CXCL5 (C-X-C motif chemokine ligand 5)
Diseases named in the same sentence as CXCL5 in open-access papers (continued):
Sharing a sentence is not in itself a finding about the gene and the disease.
cancer (continued). "Cancer cells stimulate CXCL5 secretion from CAF, which enters the bloodstream and binds to the skeletal muscle receptor to activate pro-cachexia signaling pathways." (PMID 41392310, 2025). "CXCL5 neutralization offers a novel therapeutic approach to maintain muscle mass in cancer patients." (PMID 41392310, 2025). "Here, we show that Cxcl5 plays the role of a conductor orchestrating the global metabolic remodeling necessary for cancer growth and survival in the 3D TME." (PMID 40050422, 2025). "In conclusion, these results show that CAF promote cachexia via cancer cell-inducible CXCL5 secretion." (PMID 41392310, 2025). "Together, our findings identify an unanticipated role of Cxcl5 in orchestrating the cancer metabolic reprogramming in 3D culture that is required for energy and biomass maintenance and that restricts oxidative cell death." (PMID 40050422, 2025). "This suggests cancer cells in 3D conditions require Cxcl5-dependent gene expression to grow and survive." (PMID 40050422, 2025). "CXCR-2 ligands include CXCL-1, CXCL-2, CXCL-3, CXCL-5, IL-6, CXCL-7 and IL-8, and overall CXCLs/CXCR-2 pathway is implicated in cancer and inflammation." (PMID 38672477, 2024). "This factor promotes the recruitment and activation of FAPα+ stellate cells, triggering the secretion of CXCL5 and inducing epithelial-mesenchymal transition in cancer cells, facilitating their invasion and promoting vessel co-option." (PMID 38453816, 2024). "Results indicated that chemokines CXCL3 and CXCL5 gene expression were higher in the A3 and A5 than in T2 cell lines, indicating that they were important for cancer initiation either by the effect of radiation or estrogen." (PMID 39201290, 2024). "In PDAC, specific deletion of Col1 in SMA-expressing myCAFs accelerated tumor progression by promoting SOX9 activation and Cxcl5 upregulation in cancer cells." (PMID 38453816, 2024). "For example, C-X-C motif chemokine ligand 5 (CXCL5), has been linked to inflammation, metastasis, and cancer progression and has been researched as a potential biomarker for therapeutic targeting." (PMID 38744744, 2024). "This study explored the expression, functions, and regulatory mechanisms of CXCL5 in prostate stroma and cancer cells." (PMID 39765818, 2024). "Using single cell RNA-sequencing, we observed expression of CCL8, CXCL5, CCL13 and CCL7 in cancer-associated fibroblasts (CAFs)." (PMID 39249543, 2024). "CXCL5, also known as neutrophil activating peptide 78, is secreted by cancer cells or other host cells in the TME, including macrophages, fibroblasts and dendritic cells." (PMID 39235457, 2024). "There appears to be a paucity of literature regarding the relationships of both CXCL5 and H3Cit to QoL and appetite in cancer cachexia." (PMID 38744744, 2024). "It had been known that CXCL5 mediated the NF-κB pathway, a key signaling pathway in cancer, and the PSA is the target gene of NF-κB." (PMID 39765818, 2024). "CAFs assert their pivotal role within this vicious cycle, actively shaping an inflamed neoplastic niche where IL-6, IL-11, LIF, and CXCL5 orchestrate an inflammatory phenotype that fuels cancer progression." (PMID 39609411, 2024). "CXCL1, CXCL5, and CXCL10 have generally been considered to be pro-tumorigenic in several cancer types, as they are associated with poorer prognosis and an immunosuppressive microenvironment." (PMID 39623404, 2024). "Among the most recurring ligands, we found several instances that are either invariably associated to lower survival, e.g., CXCL5, CXCL1, GAL, and RPS19, or have opposite associations depending on the cancer type, e.g., CXCL9." (PMID 38723607, 2024). "We further elucidated that high PD-L1 expression in cancer cells resulted from enhanced phosphorylation of the Paxillin (PXN)/AKT signaling pathway triggered by CXCL5 stimulation of CXCR2 in a dose-dependent manner." (PMID 39034411, 2024).
cancer (continued). "These receptors are activated by multiple signaling molecules including CXCL-1, CXCL-2, CXCL-5, CXCL-8, and IL-8 released by various constituents of this environment, including cancer cells, immune cells, and cancer-associated fibroblasts." (PMID 38361931, 2024). "They found that the chemokines CXCL8 and CXCL5 were up-regulated in high-grade sinonasal cancer, affecting leukocyte activation and trafficking, angiogenesis, metastasis and cancer cell proliferation." (PMID 39097562, 2024). "Collectively, these results illustrate that CXCL5 functions as the crosstalk between stroma and cancer cells, and CXCL5 as an antioxidant depends on CXCR2 in both WPMY-1 and LNCaP cells." (PMID 39765818, 2024). "CXC motif chemokine ligand 5 (CXCL5) and citrullinated histone H3 (H3Cit) are emerging biomarkers whose roles in cancer cachexia are mostly undetermined." (PMID 37906352, 2023). "KT alleviates the invasion of cancer cells from blood vessels to bone by inhibiting CXCL5/CXCR2 and CXCL12/CXCR4." (PMID 36674719, 2023). "The authors confirmed our reports about the high involvement of this chemokine in these processes and proved that CXCL5 is produced mainly by cancer epithelial cells to induce angiogenesis." (PMID 37848726, 2023). "CXCL5 is a chemokine endowed with angiogenetic and pro-metastatic properties, frequently overexpressed in human cancers where it is considered as a prognostic biomarker." (PMID 36934257, 2023). "PTN in the metastatic microenvironment activates the NF-κB pathway in cancer cells, leading to increased cytokine production including CXCL5, which results in elevated neutrophil recruitment and contributes to immune suppression." (PMID 36828390, 2023). "There appears to be paucity in the literature on the roles of CXCL5 and H3Cit in cancer cachexia, specifically pertaining to nutrition-related indices." (PMID 37906352, 2023). "The mean value of CXCL5 intensity score in cancer was 2.03 ± 0.151 (mean ± SE) in AA compared to 1.77 ± 0.196 in CA cases, while the intensity of staining in the adjacent benign tissue for AA was 0.99 ± 0.134 compared to 0.92 ± 0.092 in CA cases." (PMID 37698493, 2023). "In this context, CXCL5 and H3Cit are considered relatively new and less well-described biomarkers for cancer cachexia." (PMID 37906352, 2023). "More importantly, one unexpected finding was the extent to which necroptosis released CXCL5 contributing to inflammation to accelerate cancer cell migration and invasion in PC." (PMID 37371833, 2023). "TDO2 in turn activated the Kyn–AhR pathway, which enhanced glycolysis, which stimulates the anabolic growth of cancer cells and CXCL5 secretion to recruit macrophages to the tumor microenvironment." (PMID 37232717, 2023). "Mechanistically, we found PTN activates the NF-κB pathway in cancer cells, resulting in elevated expression of cytokines including CXCL5." (PMID 36828390, 2023). "Emerging evidence suggests that Schwann cells promote cancer cell metastasis by secreting C-X-C Motif Chemokine Ligand 5 (CXCL5), Interleukin 6 (IL-6), and Transforming Growth Factor Beta 1 (TGF-β), or by direct cancer cell contact." (PMID 37524695, 2023). "These areas of inconsistency are not standardized across all literature, questioning the prognostic value of CXCL5 expression in cancer patients." (PMID 37906352, 2023). "CXCL5/ENA-78 (epithelial cell-derived neutrophil-activating peptide-78) was identified as a factor in the interaction between CCA cells and cancer-associated fibroblasts." (PMID 35377900, 2022). "More recent study has shown that the cancer cell-mediated secretion of CXCL5 drives mature protumorigenic neutrophil infiltration in non-small cell lung cancer and impairs the differentiation of antitumor CD8+ T cells." (PMID 36091114, 2022). "Among cancer patients, CXCL5 is closely related to survival time, recurrence, and metastasis and is associated with a poor prognosis in ccRCC." (PMID 36417422, 2022).
cancer (continued). "As a member of the Glu-Leu-Arg (ELR) positive CXC chemokine family, CXCL5 has been identified as an inflammatory mediator with critical role in malignant tumors." (PMID 36151545, 2022). "The other phenotypic molecule identified in M‐MDSC‐like response was CXCL5, which in cancer, acts as the chemoattractant for CXCR2‐expressing MDSCs, thus promoting MDSC recruitment and infiltration into tumors." (PMID 35285058, 2022). "CXCL5 has long been documented as one of the important chemokines that are expressed by many immune cells, such as macrophages, eosinophils, and cancer cells." (PMID 35646113, 2022). "The CXC chemokines (e.g., CXCL1, CXCL2, CXCL3, CXCL5, and CXCL8) are significantly upregulated in most cancers and positively associated with cancer metastasis and chemo-resistance." (PMID 36612163, 2022). "Together, these findings provided the potential molecular mechanism of CXCL5 in of EC cells, which lay the groundwork for future research into CXCL5 as a cancer modulator and help the generation of novel regimens for EC treatment." (PMID 35936390, 2022). "The expression intensity of CXCL5 was also detected in line with the malignancy degree, metastasis, and survival of cancer patients, which provides new potential for clinical application." (PMID 35702353, 2022). "In this study, exosomal HSPC111 derived from CRC cells induces a panel of cancer-promoting factors in CAFs, including CXCL5, TGF-β, MMP2 and SERPINE1, so as to enhance their cancer-promoting effects." (PMID 35027547, 2022). "Functionally, CXCL5 promoted Cr(VI)-induced cell transformation and played an important role in maintaining cancer phenotypes of Cr(VI)-transformed BEAS-2B cells." (PMID 36497250, 2022). "Previous studies have elucidated that CXCL5 produced by fibroblasts plays an important role in the progression, growth and metastasis of cancer." (PMID 35027547, 2022). "Currently, CXCL5 has also been proved to contribute to angiogenesis and proliferation, promoting malignant progression in distinct cancers." (PMID 35150082, 2022). "By contrast, HLA-I+EMTlo cancer cells were associated with enhanced IL1A, IL1B, and CXCL5 mRNA expression." (PMID 35503263, 2022). "Another mechanism is that YAP1/TEAD directly upregulates CXCL5 in cancer cells to recruit CXCR2-expressing MDSCs, leading to decreased infiltration of CD8+ T cells." (PMID 36479120, 2022). "As for CAFs, it has been shown to promote the expression of PD-L1 by secreting CXCL5 in mice cancer cells." (PMID 34868949, 2021). "Together, these results suggest that DDR1 on cancer cells drives CXCL5 production, CD45+CD11b+Ly6G+ TAN infiltration, and liver metastasis." (PMID 34237033, 2021). "CXCL5 exerts its action by binding to its G-protein-coupled receptors chemokine receptor 2 (CXCR2), and the CXCL5/CXCR2 axis has been widely investigated in various types of cancers." (PMID 34603292, 2021). "Abnormal expression of CXCL5 is found to be correlated with a large number of diseases, such as autoinflammation, cancer, obesity, and diabetes." (PMID 34603292, 2021). "The exposure of parental cancer cells to collagen I for 3 hours increased mRNA and protein levels of CXCL5 in MDA-PATC 148 and BxPC-3 cells, which was diminished in knockdown DDR1 cells." (PMID 34237033, 2021). "Thanks to IL-6 autocrine and paracrine stimulus, CAFs upregulate VEGF, activate the JAK2/STAT3 pathway, express MCP-1, CCL11/8/20, CXCL5 and IL-9 for cancer cell invasion, growth and survival." (PMID 34944856, 2021). "We found that treatment with 7rh interrupts collagen I-mediated CXCL5 production from cancer cells, which result in NETs formation and reduced TAN recruitment." (PMID 35127700, 2021). "CXCL5 has been found to be significantly overexpressed in many cancers, including CRC, and has been shown to be an important oncogenic factor in cancer progression." (PMID 33640021, 2021).
cancer (continued). "However, the possible mechanisms leading to the up-regulation of CXCL5 in PC still remains unknown, despite previous studies on other cancers revealing that CXCL5 expression might be driven by multiple cancer-associated pathways, including nuclear factor-κB and cyclooxygenase-2/prostaglandin E2." (PMID 33458757, 2021). "Taken together, these data support that collagen I–DDR1 interaction induces CXCL5 production by cancer cells, which promotes neutrophil infiltration and NET formation to drive NET-associated cancer cell migration." (PMID 34237033, 2021). "These carefully designed studies demonstrate that CXCL5 is a soluble factor released into the media from DDR1-positive cancer cells in the presence of collagen; when exposed to CXCL5, neutrophils generate NETs that promote cancer cell invasion." (PMID 34237033, 2021). "Studies reported that CXCL5 induced the EMT process in cancer cells by activating ERK/Elk-1/Snail, AKT/GSK3β/β-catenin, or ERK/Snail signaling pathways." (PMID 34603292, 2021). "A recent study showed that cancer-educated bone marrow mesenchymal stem cells (BMSCs) do not only attract cancer cells into the circulation for distant metastasis via CXCL5/CXCR2 but also induce bone marrow-derived PMN-MDSCs." (PMID 34689842, 2021). "Cancer cells, as well as the diverse cell types of the surrounding stroma, produce cytokines and chemokines, such as CXCL5 and CXCL8 that induce neutrophil recruitment and phenotypical transition into pro-tumorigenic MDSCs." (PMID 32784743, 2020). "In regard to PCa with bone metastasis, macrophage-driven efferocytosis of PCa cells in vitro induced the expression of pro-inflammatory cytokines, especially CXCL5, and the proinflammatory environment fueled further cancer cell growth." (PMID 32346605, 2020). "CXCL5, which have been reported to recruit and activate leukocytes and play a role in cancer progression, was also indicated to be one of the most key genes in the PPI network." (PMID 32724299, 2020). "CXCL5 has recently come to the forefront in research for its involvement in proliferation, migration, invasion, and immune evasion in multiple cancer types." (PMID 32903405, 2020). "In tumors, the CXCL5/CXCR2 axis has been implicated in multiple processes, as angiogenesis, growth, metastasis and chemoresistance, acting on TME, cancer stem cells and immune checkpoints." (PMID 32784743, 2020). "In conclusion, we have shown that key mediators of necroptosis were expressed in PC, and CXCL5 released from necroptotic cells promotes cancer cell migration and invasion via CXCR2 in PC cells." (PMID 31999765, 2020). "In this study, we have shown that PC has potential to induce necroptosis, and CXCL5 released from necroptotic cells promotes cancer cell migration and invasion via CXCR2 in PC cells." (PMID 31999765, 2020). "Some of these chemokines such as CXCL1, CXCL5, CXCL6 and CXCL8 are produced at high levels by tumors cells, whereas some are also produced by blood cells, cancer associated fibroblasts or endothelial cells." (PMID 32727083, 2020). "As a member of the ELR + CXC chemokine family, C-X-C motif chemokine 5 (CXCL5) is an inflammatory mediator cells which recently has been determined to play a core role in some cancer." (PMID 33061849, 2020). "Specifically, CXCL17 and CXCL5 were increased in cancers with high proliferation as assessed by Ki67 and decreased in cancers with high ER levels." (PMID 30451357, 2019). "The chemotactic role of CXCL5 derived from cancer-educated BMSCs on LLCs was investigated in C57BL/6 mice." (PMID 31819035, 2019). "CXCL5, nitric oxide and GM-CSF produced by cancer-educated BMSCs contribute to the formation of malignant microenvironments." (PMID 31819035, 2019). "Most members of the chemokine family, including CXCL1, CXCL2, CXCL5, CXCL9, CXCL10 and CXCL13, where they are secreted by cancer or stromal cells, such as cancer-associated fibroblasts (CAFs) and dendritic cells (DCs)." (PMID 30925930, 2019).
cancer (continued). "It has been reported that the AKT, ERK, JNK, and STAT3 pathways were related to the evolution and progression of carcinoma mediated by the CXCL5/CXCR2 axis." (PMID 30792394, 2019). "We systematically searched PubMed, Embase and Web of Science to obtain all relevant articles investigating the prognostic significance of CXCL5 expression in cancer patients." (PMID 29743818, 2018). "Our results demonstrated that higher expression level of CXCL5 was significantly associated with shorter PFS and RFS in cancer patients." (PMID 29743818, 2018). "Thus, we could speculate that CXCL5 might be the indicator of the presence of putative cancer stem cells, which have been shown to be associated with the metastasis and poor prognosis of cancer patients." (PMID 29743818, 2018). "In the future, more relevant studies are warranted to investigate the role of CXCL5 in human cancer." (PMID 29743818, 2018). "In a word, this is the first meta-analysis to evaluate the relationship between expression levels of CXCL5 with prognosis of cancer patients." (PMID 29743818, 2018). "Here we performed the current comprehensive meta-analysis to systematically explore the prognostic value of abnormally expressed CXCL5 in cancer patients." (PMID 29743818, 2018). "More recently, Cxcl-5 has been shown to mediate neutrophil infiltration during cancer or infection however, it requires further processing post secretion from epithelial cells." (PMID 30365535, 2018). "Fourteen studies including seventeen cohorts reported the relationship between abnormal expression levels of CXCL5 with OS in a total of 4952 cancer patients." (PMID 29743818, 2018). "Previous studies have shown that CXCR2 can be activated by CXCL5 or other ligands to stimulate cancer progression through the activation of downstream pathways, such as JAK/STAT3, JNK, PI3K/AKT and ERK1/2 pathway." (PMID 28356111, 2017). "A: An immunoblot showing that CXCL5 is overexpressed in cancer tissues compared with the peritumoral normal tissues." (PMID 28356111, 2017). "Previous studies have reported that CXCL5 produced by fibroblasts plays a prominent role in the progression, growth and spread of various types of cancer." (PMID 28356111, 2017). "Fibroblasts are regarded as key determinants in the malignant progression of cancer through the secretion of various chemokines, including CXCL5." (PMID 28356111, 2017). "The mRNA expression of DACH1 was inversely related to CXCL5 (R value = −0.77, p<0.025) and such inverse relationship was also observed in normal and cancer tissues." (PMID 25788272, 2015). "Aberrant expression of C-X-C motif chemokine 5 (CXCL5) contributes to the progression of various cancers." (PMID 23469080, 2013). "Moreover, KLF4 links cancer cells to MDSCs: alterations in cancer‐cell KLF4 expression modulate the production of chemokines such as CXCL5, thereby influencing MDSC recruitment into the TME." (PMID 41532367, 2026). "CAF contribute to cachexia via cancer cell crosstalk that upregulates CXCL5 secretion." (PMID 41392310, 2025). "The therapeutic effect of CXCL5 neutralization on cancer cachexia may depend on whether CXCR2 signaling contributes to these differences in cachexia progression observed in males and females." (PMID 41392310, 2025). "However, further studies in male mice would be recommended for validating the role of CXCL5 in cancer cachexia and can better match hormonal regulation." (PMID 41392310, 2025). "Future studies could employ bioinformatics-based analyses of clinical data to delineate the relationship between CXCL5 levels and the severity of cachexia in cancer patients." (PMID 41392310, 2025). "The results in the current study suggest that the influence of CXCL5 levels on cancer patient survival may, at least in part, be due to an effect on the progression of cachexia." (PMID 41392310, 2025).